LINC01134 (long independently transcribed non-coding RNA 1134)
Synonyms: TLNC1
Gene: Long non-coding RNA gene on chromosome 1 (3,900,187 to 3,917,547, forward strand). Ensembl gene ENSG00000236423.
Diseases named in the same sentence as LINC01134 in open-access papers:
LINC01134 is named in the same sentence as 8 diseases in open-access papers, as found by Europe PMC text mining. Sharing a sentence is not in itself a finding about the gene and the disease. The quoted sentences say what the papers report.
hepatocellular carcinoma (9 papers, 2020 to 2024). A malignant tumor that arises from hepatocytes. "LINC01134 knockdown inhibits hepatocellular carcinoma proliferation, metastasis and promotes apoptosis, and inhibits tumor growth in vivo." (PMID 36626426, 2022). "LINC01134 was found to recruit the transcription factor SP1 to the p62 promoter in hepatocellular carcinoma, which in turn activates the antioxidant pathway of p62 and regulates the resistance to oxaliplatin by affecting cell viability, apoptosis, and mitochondrial homeostasis." (PMID 37914721, 2023). "LINC01134 has been studied only in hepatocellular carcinoma and its role in PDAC is unclear." (PMID 37914721, 2023). "TLNC1 was previously known as linc01134, which has been demonstrated to promote the progression and metastasis, as well as confer oxaliplatin resistance in hepatocellular carcinoma (HCC) by several recent studies, indicating that this lncRNA plays vital roles in HCC." (PMID 35477447, 2022). "Additional studies found that the transcription factor YY1 (yin yang 1) together with LINC01134, miR-324-5p, and IGF2BP1 (Insulin-like growth factor 2 mRNA binding protein 1), could form a positive feedback loop that mediates the progression of hepatocellular carcinoma." (PMID 37914721, 2023). "The regulatory role of linc01134 in hepatocellular carcinoma (HCC) has not been studied yet." (PMID 32272940, 2020).
liver cancer (3 papers, 2022 to 2023). An epithelial or non-epithelial malignant neoplasm that arises from the liver. "Here, we revealed the role of TLNC1, which was also known as linc01134, in tumor growth and metastasis of liver cancer." (PMID 35477447, 2022). "Silenced LINC01134 induces ferroptosis of liver cancer cells and reduces the resistance to oxaliplatin, which provides a new basis for targeted therapy of liver cancer." (PMID 35875091, 2022). "In short, the results of this study revealed LINC01134, a novel negative regulator of ferroptosis, up-regulates GPX4 expression by enhancing the recruitment of the transcription factor Nrf2 to the GPX4 promoter, thereby increasing liver cancer resistance to OXA." (PMID 35875091, 2022).
liver cirrhosis (1 paper, 2020). "Increased expression of LINC01134 is positively correlated with microvascular invasion and macrovascular invasion but not correlated with age, gender, hepatitis B surface antigen (HBs antigen), liver cirrhosis, alpha-fetoprotein (AFP), tumor size, and encapsulation." (PMID 32656205, 2020).
pancreatic cancer (1 paper, 2023). "We next investigated the role of LINC01134 in regulating the WNT5A/WNT signaling pathway in pancreatic cancer." (PMID 37914721, 2023). "We found that the expression of LINC01134 in pancreatic cancer cell lines was significantly higher than that in the normal pancreatic cell line.These results suggested that LINC01134 was highly expressed in PDAC tissues and positively correlated with the malignancy of PDAC." (PMID 37914721, 2023). "We hypothesized that LINC01134 also acts through the ceRNA mechanism in pancreatic cancer." (PMID 37914721, 2023).
tumor (8 papers, 2020 to 2025). "This tumor-specific overexpression pattern implicated LINC01134 as a potential molecular effector in HCC pathogenesis." (PMID 41304936, 2025). "Among these, LINC01134 emerged as a multifaceted regulator, driving tumor aggressiveness while suppressing triaptosis sensitivity." (PMID 41304936, 2025). "It had been shown that LINC01134 promotes HCC progression by facilitating tumor proliferation, migration, epithelial-mesenchymal transition, oxaliplatin resistance, and radioresistance." (PMID 39440055, 2024). "To further investigate the function of LINC01134 in vivo, we established a nude mouse transplantation tumor model." (PMID 37914721, 2023). "Importantly, a progressive elevation of LINC01134 expression was observed across advancing tumor stages (AJCC classification), suggesting its potential role in disease progression." (PMID 41304936, 2025). "Furthermore, we analyzed the correlation between the expression levels of LINC01134 and clinical characteristics, and the results indicated that histologic classes, clinical stages, and tumor metastasis were positively correlated with LINC01134 expression." (PMID 39440055, 2024). "Last but not least, our study was the only study that utilized both knockdown and overexpression modulation to investigate the biological functions of linc01134 in tumor growth and metastasis both in vitro and in vivo, thus it was so far the most comprehensive study of linc01134." (PMID 35477447, 2022). "In vivo assays demonstrated LINC01134 depletion hindered HCC tumor growth." (PMID 35173610, 2021). "Under 4 Gy radiation, downregulated LINC01134 further hindered tumor growth." (PMID 35173610, 2021). "Moreover, silencing LINC01134 suppressed subcutaneous tumor growth in nude mice." (PMID 39440055, 2024). "Moreover, we noticed LINC01134 reduction hampered HCC tumor growth via in vivo assays." (PMID 35173610, 2021). "Previous studies revealed that LINC01134 was a significant oncogene in HCC, participating in tumor proliferation, migration, epithelial-mesenchymal transition (EMT), drug resistance." (PMID 39440055, 2024). "Taken together, silencing of LINC01134 restricts the radioresistance in HCC and impedes HCC tumor growth." (PMID 35173610, 2021). "Linc01134 down-regulation hampered HCC cell proliferation in vitro and repressed tumor growth in vivo." (PMID 32272940, 2020).
cancer (4 papers, 2020 to 2023). A tumor composed of atypical neoplastic, often pleomorphic cells that invade other tissues. "qRT-PCR revealed that the expression of LINC01134 was significantly (p < 0.01) higher in 36 pairs of PDAC tissues than that in normal tissues adjacent to cancer." (PMID 37914721, 2023). "Whether LINC01134 regulates the metastasis of other cancers need further investigation." (PMID 32656205, 2020). "Subsequently, we examined the expression of LINC01134 in 70 patients with PDAC and found that the expression of LINC01134 was significantly higher in PDAC tissues compared with normal tissues adjacent to cancer." (PMID 37914721, 2023). "Therefore, whereas LINC01134 is more crucial in the 11LNCPS, there are hardly any published studies on AC116025.2 in any types of cancers." (PMID 35572559, 2022). "The expression and function of LINC01134 in human cancers have not been investigated." (PMID 32656205, 2020).
LINC01134 also shares sentences with these, for which no sentence is quoted: colorectal cancer (2 papers); lung disease (1).